PROB1 (proline rich basic protein 1)
Synonyms: C5orf65
Tractability: No criterion of Open Targets' tractability assessment is met for any kind of drug.
Gene: Protein-coding gene on chromosome 5 (139,390,592 to 139,395,104, reverse strand). Ensembl gene ENSG00000228672.
Subcellular location (Human Protein Atlas): Nucleoplasm
Gene Ontology:
Cellular component: nucleoplasm
Genetic constraint (gnomAD): Missense variants: 1,102 observed, 989.28 expected, observed/expected ratio (o/e) 1.11, 90% interval 1.06 to 1.17. Synonymous variants: 481 observed, 455.58 expected, observed/expected ratio (o/e) 1.06, 90% interval 0.98 to 1.14.
Homologues: Orthologues: chimpanzee PROB1 (99% identical), macaque PROB1 (92% identical), pig PROB1 (73% identical), rabbit PROB1 (72% identical), dog PROB1 (72% identical), rat Prob1 (69% identical), mouse Prob1 (68% identical), guinea pig PROB1 (59% identical).